MTA2 (metastasis associated 1 family member 2)
Diseases named in the same sentence as MTA2 in open-access papers (continued):
Sharing a sentence is not in itself a finding about the gene and the disease.
cancer (continued). "The primary features and molecular mechanism of MTA2 in different cancer types." (PMID 41159000, 2025). "We analyzed the location of MTA2 in human cells and concluded that MTA2 played a regulatory role mainly in the nucleus and cytosol, which can provide hints for the regulatory study of MTA2 in cancer cells." (PMID 37371463, 2023). "MTA2 serves as a pivotal nexus for coordinating cytoskeletal organization and transcription, establishing a crucial connection between nuclear cytoskeletal dynamics and promoting cancer metastasis." (PMID 37887327, 2023). "Human β-defensin-3 (HBD3) inhibits cancer cell metastasis by downregulating MTA2." (PMID 38069041, 2023). "We also created forest plots to investigate the OS, DFS, DSS, and PFS of MTA2 in 33 cancer types." (PMID 37371463, 2023). "This meant that MTA2 probably influences cancer progression by regulating immune pathways." (PMID 37371463, 2023). "Our study demonstrated that MTA2 was highly expressed in 19 out of 33 types of cancer." (PMID 37371463, 2023). "Subsequently, we also analyzed the relevance of MTA2 and immune genes in pan-cancer." (PMID 37371463, 2023). "From existing studies and our findings, we speculated that cancer patients with high MTA2 expression and high TMB and MSI would probably have a better prognosis after ICIs treatment." (PMID 37371463, 2023). "This study provides a prospective view on the importance of MTA2 in cancer immunotherapy, revealing correlations between basic immune indicators and MTA2, which may facilitate the understanding of the immune system and the underlying mechanisms of MTA2." (PMID 37371463, 2023). "The MSigDB database was used to analyze the MTA2 and pan-cancer immune linkages." (PMID 37371463, 2023). "Moreover, the prognostic value of MTA2 in LIHC was the most significant among 33 cancer types (p < 0.05)." (PMID 37371463, 2023). "Therefore, the aim of our study is to explore the prognostic value of MTA2 in 33 cancer types and to investigate its potential immune function." (PMID 37371463, 2023). "We also explored the association of MTA2 expression with MSI and TMB in 33 cancer types." (PMID 37371463, 2023). "In summary, combining previous reports and our results, we speculated that MTA2 could be a target for cancer immunotherapy." (PMID 37371463, 2023). "MTA2 has been reported to be frequently genetically amplified in human cancers, and upregulation of MTA2 could promote cancer metastasis and progression." (PMID 37371463, 2023). "MTA2 is amplified in a variety of cancers, including HCC, thyroid cancer, and ovarian cancer." (PMID 37371463, 2023). "We also analyzed MTA2 expression at different stages of pan-cancer." (PMID 37371463, 2023). "Thus, our finding that MEQ inhibited the expression of VEGFA in TNBC through the MTA2/SerRS/VEGFA pathway revealed the underlying mechanism for isoflavones and their derivatives, allowing the optimization of this natural molecule for cancer treatment." (PMID 32944400, 2020). "Considering the potential role of PTEN in regulating the PI3K/AKT pathway in the cancer cells, we next determine if the MTA2-mediated PTEN inhibition might affect PI3K/AKT signaling." (PMID 30814496, 2019). "Since MTA2TR is adjacent to MTA2 gene, which is an oncogenic driver in numerous cancers, we wonder whether MTA2TR exerts cis-acting effect on MTA2 expression." (PMID 31410216, 2019). "This evidence provided support to the hypothesis that MTA2 could act as an oncogene in many cancers." (PMID 29743816, 2018). "Finally, among the few genes downregulated in EXO/miR-222 we detected MTA1 and MTA2, nuclear receptor coregulators overexpressed in human cancers, but reported to play a dual role being either corepressors or coactivators." (PMID 26912358, 2016). "The mechanisms of MTA2 in regulating cancer cell mobility and invasion were unclear." (PMID 24010737, 2013). "In contrast to MTA1 and MTA2, which are usually upregulated in cancer, MTA3 is downregulated." (PMID 23671646, 2013).
cancer (continued). "The fact that the NuRD complex contains MTA2, which is associated with cancer metastasis, provides further evidence that HDAC1 may play a role in cancer development." (PMID 17022812, 2006). "Furthermore, we discuss the upstream regulation of MTA2 by transcription factors, microRNAs and lncRNAs in specific physiology and pathology conditions, which results in the abnormal MTA2 expression in various aspects of cancer." (PMID 41159000, 2025). "Finally, we investigated the biological function of MTA2 in cancer." (PMID 37371463, 2023). "Therefore, it is necessary to conduct a pan-cancer analysis of MTA2." (PMID 37371463, 2023). "In the current study, there is a correlation between MTA2 expression and RNASET2 expression, as well as cancer cell migration in ccRCC cells." (PMID 36728187, 2023). "Conversely, MTA2, DDX46, CDCP1, and CELF1, which have been reported to play a role in at least one of these processes in CRC, are known to promote cancer." (PMID 37510319, 2023). "Our study indicated that MTA2 expression was positively correlated with TMB in 12 cancer types and with MSI in 8 cancer types." (PMID 37371463, 2023). "TWIST1 also co-purified with NuRD complex, including MTA2, HDAC2, and RbAp48 in SW480 cells, which is consistent with previous findings in other cancer cell lines." (PMID 35884488, 2022). "Although both MTA1 and MTA2 are among the most upregulated in human cancers, their functions do not always overlap." (PMID 41159000, 2025). "Through effective MTA2 inhibition and disruption of downstream oncogenic signaling, AS1411-Lipm[siRNA] demonstrates a strategy that directly addresses the challenges of siRNA-based cancer therapy and the broader limitations of PDAC treatment." (PMID 40943389, 2025). "Despite growing evidence that MTA2 plays a crucial role in the tumorigenesis of certain cancers, no systematic pan-cancer analysis of MTA2 is available to date." (PMID 37371463, 2023). "This may suggest that MTA2 expression levels affect TMB and MSI in cancers, thereby influencing the response of cancer patients to immune checkpoint inhibition therapy." (PMID 37371463, 2023). "Our finding that MTA2 could be targeted by MEQ also provides a way to manipulate MTA2-mediated gene expression, which could be developed for cancer treatment." (PMID 32944400, 2020). "We found, for instance, that 6 cancer-related targets changed their expression levels: HSPD1, PARP1, XRCC5, PRDX2, MTA2 and FASN." (PMID 24801752, 2014). "However, so far, most studies on MTA2 are limited to a specific type of cancer, and there is no systematic analysis of MTA2 pan-cancer." (PMID 37371463, 2023). "The biological functions of MTA2 in cancer have not been fully investigated." (PMID 25929737, 2015). "Functional studies have demonstrated that, unlike MTA1 and MTA2, which predominantly facilitate tumor progression, MTA3 was initially reported to suppress cancer cell invasion and metastasis." (PMID 41584603, 2025).
infection (3 papers, 2010 to 2026). The state of being infected such as from the introduction of a foreign agent such as serum, vaccine, antigenic substance or organism. "We conclude that HDAC1 and a second component of the NuRD complex, MTA2, interact either directly or indirectly with both HCMV pUL29/28 and pUL38 proteins during infection." (PMID 20585571, 2010).
hematological malignancies (1 paper, 2022). "In hematological malignancies, studies relating to MTA2 remain limited." (PMID 36454786, 2022).
MTA2 also shares sentences with these, for which no sentence is quoted: tauopathies (20 papers); Alzheimer disease (3); COVID-19 (2); lip (2); amyloid (1); argyrophilic grain disease (1); brain tumors (1); CHARGE syndrome (1); cholangiocarcinoma (1); colorectal cancer (1); depression (1); eczema (1); endometrial cancer (1); Fanconi anemia (1); head and neck cancer (1); lung squamous cell carcinoma (1); lupus (1); Lymph Node (1); malignant melanoma (1); mesothelioma (1); metastatic tumors (1); multiple myeloma (1); oesophageal cancer (1); oral cancer (1); ovarian serous cystadenocarcinoma (1); papillary thyroid cancer (1); paraganglioma (1); pheochromocytoma (1); Pick disease (1); progressive supranuclear palsy (1).
A further 4 diseases each share a sentence with MTA2 in 1 paper.